MIR6724-3 (microRNA 6724-3)
Synonyms: hsa-mir-6724-3
Gene: MicroRNA gene on chromosome 21 (8,388,362 to 8,388,453, forward strand). Ensembl gene ENSG00000277379.
Homologues: Paralogues in human: MIR6724-1 (100% identical), MIR6724-2 (100% identical), MIR6724-4 (100% identical).